LRRK2 (leucine rich repeat kinase 2)
Diseases named in the same sentence as LRRK2 in open-access papers (continued):
Sharing a sentence is not in itself a finding about the gene and the disease.
tauopathy (31 papers, 2013 to 2025). Neurodegenerative disorders involving deposition of abnormal tau protein isoforms (tau proteins) in neurons and glial cells in the brain. "Recent GWAS investigating the rate of progression of a tauopathy in progressive supranuclear palsy identified variants in a putative enhancer for LRRK2 that increase the rate of progression, implicating LRRK2 in mediating tauopathy pathogenesis." (PMID 40790356, 2025). "Mutations in LRRK2 are also associated with pathologically confirmed primary tauopathies, such as PSP or CBD." (PMID 38554150, 2024). "The recent discovery that variation at the LRRK2 locus is associated with the progression of PSP highlights the potential importance of LRRK2 in tauopathies." (PMID 35815712, 2022). "This survival signal for a primary tauopathy is 190 kb from the PD LRRK2 association SNP rs76904798." (PMID 35815712, 2022). "In terms of neurodegeneration, variants in the LRRK2 locus have recently been identified through GWAS as candidates for increased survival in the tauopathy PSP." (PMID 34397087, 2021). "We show these epitopes to be hyperphosphorylated in a range of human tauopathies and in individuals with the G2109S LRRK2 mutation using our novel antibodies." (PMID 24113872, 2013). "Of the 13 cases with PEP and unclassifiable tauopathy we identified 1 case with both LRRK2 G2019S mutation and a heterozygous variant in MAPT exon 4 (c.370C>G, p.Q124E)." (PMID 23664753, 2013). "In addition to being causative for LRRK2 PD, LRRK2 variants increase risk for development of iPD and the primary tauopathy PSP." (PMID 40661559, 2025). "Indeed, pathogenic LRRK2 variants have been associated with various proteinopathies including AD, various tauopathies including PSP, corticobasal degeneration (CBD), familial frontotemporal degeneration (FTD), TDP-43-associated neurodegeneration." (PMID 39108519, 2024). "Larger cohorts are warranted to further explore the LRRK2 mutation mechanisms related to Tauopathy and determine whether a high PSP risk can be explained by novel mutations." (PMID 36982356, 2023). "Besides increasing PD risk, LRRK2 alleles can rarely cause tauopathies, such as progressive supranuclear palsy, and also influence susceptibility for inflammatory bowel disease, leprosy, and cancer." (PMID 36100231, 2023). "Interestingly, an association between changes in tau pathology and LRRK2 mutations was identified in tauopathy." (PMID 38020716, 2023). "Our data, in aggregate, demonstrate that LRRK2 directly phosphorylates tau at T149 and T153 in vitro and the ability of LRRK2 to phosphorylate tau at these sites may underlie its ability to promote tauopathy in our novel mouse model." (PMID 24113872, 2013). "If LRRK2 is a novel tau kinase, it is possible that it may phosphorylate novel tau epitopes; however, published studies have focused on a subset of the phospho-epitopes that are frequently associated with human tauopathies." (PMID 24113872, 2013). "The involvement of LRRK2 and LRP1 in both tau and synuclein uptake by human neurons addresses questions about the role of LRRK2 in tauopathies and the mechanistic links between the pathogenesis of PD and AD and other tauopathies, while opening some new ones." (PMID 40790356, 2025). "The spatial and temporal increase in LRRK2 coincides with the phosphorylation of Thr175 tau, a critical phospho-epitope in the pathogenesis of tauopathies." (PMID 38026695, 2023). "These highlight the potential importance of LRRK2 in tauopathies, providing further support for the use of LRRK2 inhibitors." (PMID 38020716, 2023). "LRRK2 has repeatedly been recognized as an inflammatory mediator, but the role of inflammation in tauopathies such as PSP remains to be fully investigated." (PMID 35815712, 2022). "The accumulation of insoluble and phosphorylated tau was observed in a transgenic LRRK2 mouse model of tauopathy." (PMID 36233046, 2022).
tauopathy (continued). "There are a number of open questions relating to our understanding of the role of LRRK2 in tauopathies." (PMID 35815712, 2022). "The kinase cascade from LRRK2 to TAOK, PAR-1, and finally to tau phosphorylation has been proposed as a pathological transformation in tauopathy and axonal pathology in the brains of LRRK2-overexpressing mice and in human PD patients." (PMID 33050415, 2020). "Having identified T149 and T153 on tau as primary targets of direct G2019S LRRK2 phosphorylation in vitro, we then sought to determine the relevance of these sites to human tauopathy." (PMID 24113872, 2013). "We demonstrated that human WT LRRK2 expression in a mouse model of tauopathy enhances tau aggregation and tau hyperphosphorylation—critical features of human tauopathy." (PMID 24113872, 2013). "An important feature of human tauopathy and a subset of mutant LRRK2 carriers is the aggregation of tau." (PMID 24113872, 2013). "In the current study, we combined in vitro, cell culture, and novel transgenic studies to demonstrate that tau is a substrate of LRRK2 and that this interaction promotes tauopathy." (PMID 24113872, 2013). "Also, monomeric LRRK2 augments the Tau neurotoxicity, while expression of the wild form of LRRK2 or the mutant that enhances oligomerization of the protein can rescue tauopathy conditions." (PMID 40148800, 2025). "Notably, while most LRRK2-PD autopsies reveal αSyn Lewy bodies, a surprisingly wide spectrum of pathologic changes have been documented in a subset of cases, including tauopathy or, rarely, even TDP-43 protein inclusions." (PMID 36100231, 2023). "The evidence of VPS35D620N resulting in enhanced LRRK2 kinase activity further suggests that tau pathology could be present in VPS35D620N PD, as tauopathy is a hallmark of LRRK2 PD." (PMID 34397087, 2021). "Importantly, we demonstrate that expression of transgenic LRRK2 in a mouse model of tauopathy increased the aggregation of insoluble tau and its phosphorylation at T149, T153, T205, and S199/S202/T205 epitopes." (PMID 24113872, 2013). "Although our in vitro results suggest that the increase in tauopathy in the LRRK2/TauP301L mice is likely derived from the kinase function of LRRK2, it is possible that in vivo LRRK2 also promotes the aggregation of tau into the insoluble fraction by indirect cellular mechanisms." (PMID 24113872, 2013). "This could support a potential interaction of LRRK2 and tau in LRRK2/TauP301L mice as tau switches from its highly soluble (normal) state to the insoluble protein that is found in tauopathy." (PMID 24113872, 2013). "The rTg4510 model represents a well-characterized model, providing a “primed system” in which we could determine if human LRRK2 phosphorylates tau in vivo and if this could influence the development of tauopathy." (PMID 24113872, 2013). "The pT149 and pT153 immunostaining in these diverse cases of human tauopathy suggests that further studies on the role of LRRK2 in these disorders could be informative." (PMID 24113872, 2013). "Further, the presence of phosphorylation at tau T149 and T153 in a variety of tau pathologies suggests that LRRK2 genetic studies in human tauopathies may be warranted." (PMID 24113872, 2013). "Finally, we demonstrate that human wild-type LRRK2 expression in a mouse model of tauopathy enhances tau aggregation and tau hyperphosphorylation—critical features of human tauopathy." (PMID 24113872, 2013). "Alternatively, either the clinical diagnosis of progressive supranuclear palsy (PSP), which was the only tauopathy diagnosis in the cohort, the relatively young age at death compared to the other LRRK2 cases, or other factors may affect the presence of particulate PLA." (PMID 40314782, 2025).
tauopathy (continued). "While multiple studies have suggested that LRRK2 mutations are not independently associated with primary tauopathies such as progressive supranuclear palsy or corticobasal degeneration, Alzheimer’s disease-type tau pathology still appears consistently with LRRK2- and idiopathic PD." (PMID 38438877, 2024). "Here, we review the recent research particularly with respect to LRRK2 in tauopathies, and highlight important questions that need to be addressed as we advance toward disease-modifying therapies as there is emerging evidence that LRRK2 may be a therapeutic target beyond PD." (PMID 35815712, 2022). "Similarly to LRRK2, VPS35 has been associated with tauopathies in in vivo and in vitro modelling." (PMID 34397087, 2021). "Finally, if elevated LRRK2 kinase activity is directly modulating tau pathology, then LRRK2 inhibitors, which are already in clinical trials for PD, may modulate tau pathology in other primary tauopathies." (PMID 31733655, 2019). "LRRK2 is not known to play a role in tauopathies beyond its involvement in PD, but it is possible that rare genetic variants in LRRK2, including those that confer risk to PD or have yet to be uncovered, could play a role in tauopathies." (PMID 24113872, 2013). "Human LRRK2 expression in LRRK2/TauP301L mice did not affect human tau levels in the normal (soluble) fraction when compared to TauP301L mice alone, ensuring that any effects on tauopathy in the LRRK2/TauP301L mice would not be due to expression artifact." (PMID 24113872, 2013).
cognitive decline (30 papers, 2013 to 2026). "Previous studies have consistently reported that LRRK2 mutation carriers with PD exhibit slower cognitive decline or milder cognitive symptoms than non‐carriers." (PMID 39129413, 2024). "In contrast, however, in our longitudinal analysis of the asymptomatic LRRK2 cases, a smaller brain-age gap was associated with faster cognitive decline." (PMID 39713239, 2024). "In contrast, PD patients with LRRK2 mutations generally show a more motor-predominant disease course with less cognitive decline and slower disease progression." (PMID 38951174, 2024). "In this review, we summarize data regarding cognitive function on clinical studies, neuroimaging, and biological markers of cognitive decline in autosomal dominant PD linked to mutations in LRRK2 and SNCA, autosomal recessive PD linked to Parkin and PINK1, and also PD linked to GBA mutations." (PMID 35003622, 2021). "Previous detailed studies, which included an extensive neuropsychological assessment, have shown variable results regarding cognitive decline in LRRK2 carriers." (PMID 40722695, 2025). "The rs10005233-T SNCA variant is associated with both RBD and increased cognitive decline, while the LRRK2 p.G2019S variant is associated with reduced risk of RBD and reduced cognitive decline." (PMID 40998812, 2025). "Overall, these results indicated that the two LRRK2 G2019S-PD patients were very distinct, with the Mut1 patient showing a more advanced PD stage with motor and cognitive decline than Mut2, indicating involvement of several neuronal cell populations." (PMID 38275734, 2024). "Functional neuroimaging techniques to evaluate cerebral metabolic abnormalities related to cognitive decline have been sparsely investigated in LRRK2-PD." (PMID 35003622, 2021). "In sensitivity analysis limited to individuals with known Ashkenazi Jewish ethnicities, the slope of cognitive decline in LRRK2/GBA PD remained less than GBA PD." (PMID 33881531, 2021). "Cognitive decline has been reported in approximately 23% of LRRK2-PD patients in a recent systematic review." (PMID 35003622, 2021). "LRRK2 mutation carriers usually present with lower risk of cognitive decline than IPD patients, and in general cognitive decline and psychiatric features are rarely reported in symptomatic LRRK2 mutation carriers." (PMID 23938341, 2013). "A similar trend towards slower cognitive decline was observed in LRRK2 PD compared to sporadic PD." (PMID 40773926, 2025). "Given that LRRK2-related PD typically presents with a milder phenotype, less cognitive decline, and improved prognosis, CBFB expansion may represent an adaptive cholinergic response." (PMID 41262973, 2025). "In addition, there was a trend towards or statistically significant slower cognitive decline in LRRK2 PD compared to sporadic PD in α-syn SAA positive and negative cases, respectively." (PMID 40236424, 2025). "These previous studies implied that miR-205-5p and miR-6800-5p may slow down the rate of cognitive decline among PD patients by regulating expression of LRRK2." (PMID 38765669, 2024). "CSF biomarkers of cognitive decline have been rarely assessed in LRRK2-PD." (PMID 35003622, 2021). "There has been less focus on cognitive decline in LRRK2 mutation carriers without motor signs and who do not convert to PD." (PMID 33584195, 2021). "Her clinical symptoms were confirmed in other patients with LRRK2 pathogenic variants such as tremors, akinesia, rigidity, gait disturbance with good response to levodopa, and dysautonomia, without cognitive decline or psychosis." (PMID 33918221, 2021). "About half of the LRRK2 PD patients developed cognitive decline as the disease progressed." (PMID 33584195, 2021). "We can therefore speculate that the SNCA rs10005233 variant associated with PD + RBD might also be associated with the body-first subtype of PD, whereas the LRRK2 p.G2019S variant might be associated with the brain-first PD subtype, with less frequent RBD and milder cognitive decline." (PMID 40998812, 2025).
cognitive decline (continued). "While LRRK2 and GBA1 mutations are both associated with increased basal forebrain volume at asymptomatic stages, this increase persists at the symptomatic PD stage only in LRRK2 and might be related to slower cognitive decline in these patients." (PMID 38951174, 2024). "Similarly, among participants without a GBA variation, carrying a LRRK2 G2019S variation was associated with a slower cognitive decline (LRRK2 PD vs idiopathic PD) as well as among individuals with LRRK2/GBA variations (LRRK2/GBA PD vs GBA PD)." (PMID 33881531, 2021). "Although the link between increased pS935 levels and increased pS1292 levels remains unclear, these findings indicate that changes in the activation state of LRRK2, pS1292‐LRRK2 in urinary exosomes and pS935‐LRRK2 in PBMCs, may be used to predict cognitive decline." (PMID 32652692, 2020). "In conclusion, while LRRK2 and GBA1 mutations are both associated with a specific increase in basal forebrain volume at the asymptomatic stage, this increase persists at the symptomatic PD stage only in LRRK2 carriers and might be related to the slower rate of cognitive decline in these patients." (PMID 38951174, 2024). "Finally, conclusions about the underlying mechanisms for previously unexpected effects, such as the inverse association of brain-age gap with cognitive decline in asymptomatic versus LRRK2-PD cases, were drawn post hoc and could not be tested confirmatively." (PMID 39713239, 2024). "Longitudinal cognitive decline in patients with GBA-PD was more severe than in those with LRRK2/GBA-PD, which more closely resembled LRRK2-PD." (PMID 38203667, 2023). "There was also a novel statistical interaction between LRRK2 G2019S and GBA variations in cognitive decline." (PMID 33881531, 2021). "Our study also expands prior work by identifying a novel statistical interaction between LRRK2 G2019S variations and GBA variations in cognitive decline." (PMID 33881531, 2021). "Cognitive decline in participants with LRRK2/GBA PD was less severe than in those with GBA PD and more closely resembled that observed in participants with LRRK2 PD." (PMID 33881531, 2021). "Whereas in sporadic PD the APOE ε4 allele was associated with faster cognitive decline than APOE ε3 or ε2 alleles, no APOE effect was observed in GBA1-PD or LRRK2-PD." (PMID 41730900, 2026). "This suggests that the relatively smaller brain-age gap in the asymptomatic LRRK2 cases represents a reactive rather than a compensatory mechanism, as the presence of this effect predicted a faster cognitive decline." (PMID 39713239, 2024). "Most studies suggest that LRRK2-related PD displays less non-motor symptoms compared to PD noncarriers: 23% and 32% presented cognitive decline and psychiatric disturbances, respectively." (PMID 36291241, 2022). "There was a slower, although not statistically significant, rate of cognitive decline for carriers with a LRRK2 G2019S variation compared with individuals with idiopathic PD for LRRK2 PD alone (B [SE], 0.10 [0.06] points/y; P = .08) and LRRK2/GBA PD (B [SE], 0.08 [0.05] points/y; P = .12)." (PMID 33881531, 2021). "α-synuclein levels in CSF in LRRK2-PD have been recently explored showing higher levels in LRRK2-PD compared with IPD, but their correlation with cognitive decline has not been explored." (PMID 35003622, 2021). "Interestingly, human subjects that carry both the LRRK2 G2019S variant and an additional variant in GBA1 do not have a worse clinical course of PD than those that carry a variant in either gene and, in fact, may have a beneficial effect with respect to cognitive decline." (PMID 40770658, 2025).